PRLR (prolactin receptor)
Diseases named in the same sentence as PRLR in open-access papers (continued):
Sharing a sentence is not in itself a finding about the gene and the disease.
breast cancer (continued). "Taken together, our studies have demonstrated essential role of ERα and STAT5b in EGF/EGFR induced activation of PRLR gene transcription/expression in breast cancer cells via STAT5b interaction with ERα and complex formation with Sp1/C/EBPβ at the PRLR promoter in the absence of estrogen." (PMID 27564112, 2016). "Tamoxifen treatment also delayed tumorigenesis in other mouse models of estrogen-receptor-negative mammary tumors, and the lack of prolactin-receptor expression reduced proliferation in early lesions and delayed SV40-driven tumorigenesis, but did not affect growth of the tumors once they occurred." (PMID 23369183, 2013). "To test whether GH signaling in human T47D breast cancer cells, which express low levels of GHR and high levels of PrlR, is affected by extracellular acidosis, we assessed GH induction of phosphorylation of Jak2, Jak1 and Stat5 across a range of zinc ion concentrations at pHe 7.4 and 6.8." (PMID 24004716, 2013). "The aim of this study was to expand our current knowledge about the influence of PRL on canine mammary tumorigenesis by evaluating PRLR expression in non-neoplastic canine mammary tissue and in benign and malignant mammary tumors by means of semi-quantitative real time (TaqMan) PCR." (PMID 22647582, 2012). "PRLR transcripts have been described in up to 90% of breast cancers suggesting that their presence or absence may not be as important as the distribution of the isoforms." (PMID 21144038, 2010). "In ER-positive/PR-negative luminal B-like breast cancer cells, however, FASN signaling might be co-opted as a negative regulator of the epithelial cell phenotype and, accordingly, its blockade might promote the restoration and activation of prolactin/PRLR-driven differentiation programs." (PMID 33335078, 2020). "A bsAb binding both HER2 and PRLR was conjugated to DM1 using a non-cleavable linker and showed superior in vitro activity compared to an “in house” generated HER2-DM1 ADC in breast cancer cell lines expressing both receptors." (PMID 36046842, 2022). "Unlike another target for breast cancer HER2 (expressed in most normal epithelial cells), PRLR is only slightly expressed in normal breast tissues." (PMID 32398042, 2020). "Collectively, our data indicates that at physiological zinc ion levels GH-induced Stat5 activation via PrlR, but not GHR, in breast cancer cells is significantly suppressed by moderate extracellular acidosis." (PMID 24004716, 2013). "Importantly, using CRISPR knockout of the PRLR in MCF7, HR+ breast cancer cells, further revealed that the negative relationship between PRL/PRLR pathway and YAP-CCN2 pathway is critical in suppressing luminal-to-basal stem-like lineage plasticity." (PMID 40157909, 2025). "However, no antitumor activity was found in the clinical trial of PRLR antagonist LFA102 in patients with mCRPC and advanced breast cancer." (PMID 38341429, 2024). "For PRLR and GHR no detailed studies on histopathological subtypes or their possible prognostic value in canine mammary tissue have been carried out yet in contrast to human breast cancer." (PMID 27649560, 2016). "Because T47D cells express high endogenous levels of the PRLR LF, but do not exhibit increases in LKB1 mRNA or protein following treatment with PRL, we evaluated the responsiveness of the LKB1 promoter to PRL in this breast cancer cell line." (PMID 24913037, 2014). "Accordingly, the restoration/activation of prolactin/PRLR signaling has been shown to promote cell differentiation and reverse highly proliferative, invasive, mesenchymal and tumorigenic phenotypes, such as those of the ER/PR double-negative MDA-MB-231 breast cancer model." (PMID 33335078, 2020).
hyperprolactinemia (25 papers, 2007 to 2025). Abnormally high level of prolactin in the blood. "This is supported by the discovery of prolactin receptor expression on insulin-secreting cell lines, with chronic hyperprolactinemia also being linked to impaired insulin secretion." (PMID 38645431, 2024). "Although these studies identified several inactivating PRLR variants, some activity was retained by all the variants, in contrast to the hyperprolactinaemia-associated His188Arg variant, which abolishes signalling." (PMID 36445946, 2023). "In contrast, an inactivating germline heterozygous PRLR variant (His188Arg) was reported in a kindred with hyperprolactinaemia, while an inactivating compound heterozygous PRLR variant (Pro269Leu/Arg171Stop) was identified in an individual with hyperprolactinaemia and agalactia." (PMID 36445946, 2023). "The effects on PRLR signaling were assessed together with that of the His188Arg mutant PRLR ECD that has been reported to result in a loss of function in association with familial hyperprolactinaemia." (PMID 30445560, 2019). "We therefore investigated the hypothesis that PRLR variants, resulting in aberrant PRLR signaling, may be associated with prolactinoma and hyperprolactinaemia in humans." (PMID 30445560, 2019). "Previous study has shown that the expression of PRLR in pregnant gilts with hyperprolactinemia has a downward trend." (PMID 37373417, 2023). "Using real-time PCR and flow cytometry, we found that different subsets of immature (transitional) and mature (follicular, marginal zone) B cells express different levels of the prolactin receptor and are differentially affected by hyperprolactinaemia." (PMID 22404893, 2012). "They reported PRLR negativity in 17 patients with hyperprolactinaemia as an independent predictor for short-term prognosis." (PMID 21505459, 2011). "This study investigates whether calcium and vitamin D supplementation affects prolactin receptor (Prlr) gene expression in the duodenum, vertebrae, and kidneys of female rats with sulpiride-induced hyperprolactinemia." (PMID 38929559, 2024). "In addition to the local detection of PRL and PRLR, hyperprolactinemia was also reported in 36%11 and 44%36 of GBM patients." (PMID 31862900, 2019). "The deletion of the PRLR-encoding gene leads to aggressive pituitary tumors in mice, while homozygous deletion mutants of PRLR in patients with hyperprolactinemia and agalactia do not lead to pituitary tumors." (PMID 33574795, 2020). "In another study, metoclopramide-induced hyperprolactinemia was reported to not alter pituitary PRLR expression in either OVX or intact female mice." (PMID 24859278, 2014).
breast tumor (22 papers, 2008 to 2025). "In postmenopausal women with increased PRL and PRLR there is an increased risk of developing breast tumors and metastasis." (PMID 34572912, 2021). "Together, these results indicate a loss of concomitant expression of PRLR with TGFβ receptors in invasive and advanced stage breast tumors." (PMID 30987013, 2019). "High PRLR expression in the primary breast tumour was associated with a shorter time to the clinical presentation of bone metastasis." (PMID 27782069, 2016). "The gene encoding the prolactin receptor is also highly expressed in a subset of breast tumours with poor prognosis and is part of a set of prognostic gene markers." (PMID 19014541, 2008). "Utilizing a different cohort, we found that PRLR expression in the breast tumor alters how well the cancer can repair its DNA after radiotherapy and also plays a role in activating the immune system against the tumor." (PMID 40723262, 2025). "EGF released by the stromal microenvironment surrounding the breast tumor activates signaling cascades that overlap with PRLr signaling cascades upon activation with PRL secreted by breast tumor cells." (PMID 40160874, 2025). "One case with neuroendocrine differentiation of a unilateral breast tumor was reported in a 40 year-old female with positive immunostaining for PRLr." (PMID 40160874, 2025). "A growing body of evidence revealed that the activation of prolactin (PRL) receptor (PRLR) and erythroblastic leukemia viral oncogene homolog receptor (ErbBR) endorses oncogenesis in mammary glands, supports breast tumor growth, and induces chemoresistance." (PMID 37415164, 2023). "Extracellular matrix components in the breast tumor microenvironment can also influence PRL/PRLR signaling." (PMID 36187116, 2022). "Elevated levels of PRLR in breast tumors, high circulating levels of PRL and increased expression of ERBB1/2 in patients that become resistant to endocrine therapy have shown to be associated with higher risk of cancer progression." (PMID 34572912, 2021). "PRLR is expressed at a higher level in tumors when compared to surrounding normal tissues with maximal expression in 70–95% of primary breast tumors." (PMID 34572912, 2021). "PRL/PRLR signaling can also influence the breast tumor microenvironment through extracellular matrix components." (PMID 34572912, 2021). "Multiple PRLR positive breast tumor cell lines including triple negative and low PRLR expressers are also sensitive to ABBV-176." (PMID 34107902, 2021). "Fusion protein MICA-G129R when circulating into breast tumor will adhere the MICA back to the surface of breast tumor cells through the binding of the G129R to PRLR." (PMID 34077462, 2021). "PRLR is expressed in many human breast tumors where its levels are elevated compared to normal breast tissue." (PMID 34107902, 2021). "In the current study, we found that H53 showed good antagonistic properties in vivo and in vitro, not only inhibiting GHR/PRLR-mediated intracellular signals, but also blocking breast tumor proliferation." (PMID 33362552, 2020). "We prepared the GHR/PRLR dual-effect antagonist (H53) by anti-idiotypic antibody strategy, and found that H53 exhibits potential effects against breast tumors." (PMID 33362552, 2020). "In conclusion, ccurrent research shows that H53 is a new inhibitor of GHR/PRLR which has potential as a reagent for the treatment of breast tumors." (PMID 33362552, 2020). "We also detected PRLR expression on circulating tumour cells in peripheral blood and in paired primary breast tumour and bone metastatic samples." (PMID 27782069, 2016). "Recently, the demonstration of impaired PRLR degradation in breast tumors correlated with enhanced PRLR expression." (PMID 21655368, 2008). "Although expression of the prolactin receptor is more often found in oestrogen receptor-positive breast tumours, which tend to have a better prognosis, it is also found in many oestrogen receptor-negative breast tumours." (PMID 19014541, 2008).
breast tumor (continued). "One proposed theory is that excess circulating testosterone can be aromatized into estrogen, which has been shown to increase human prolactin receptor gene expression within the peripheral tissues, which in turn directly stimulates breast tumor cell proliferation." (PMID 40160874, 2025). "Prior study has shown that blocking simultaneously ERα and PRLR pathway could effectively inhibit breast tumor growth in animal models." (PMID 38898487, 2024). "Furthermore, studies have illustrated an essential connection between PRLR and the progression of breast tumors." (PMID 36945262, 2023). "PRLR and EGFR/HER2 crosstalk, which greatly increases the activation of the RAS/ERK and PI3K/AKT pathways, are associated with poor prognosis and therapeutic resistance in breast tumor patients." (PMID 36187116, 2022). "We believe that overexpression of EGFR/HER2 and PRLR in breast tumors could maximize the actions of their ligands, and further induce cell proliferation promoting malignancy." (PMID 34572912, 2021). "Another hormone receptor which is overexpressed in most of the ER+ breast tumors is the PRLR." (PMID 34572912, 2021). "In both in vitro and in vivo assays, ABBV-176 exhibits potent cytotoxicity against multiple cell line and patient-derived xenograft breast tumor models, including triple negative and low PRLR expressing models insensitive to monomethyl auristatin (MMAE) based PRLR ADCs." (PMID 34107902, 2021). "Therefore, simultaneous treatments targeting both the HER2 and PRLR signaling cascades may offer better outcomes by efficiently hindering breast tumor progression and ameliorating endocrine resistance." (PMID 36187116, 2022). "Many breast tumors are characterized by reduced STAT5, high levels of PRLR expression, and MAPK signal components including AP-1 and pro-invasive matrix metalloproteinases." (PMID 34572912, 2021). "Several studies have indicated that overexpression of PRLR, EGFR and HER2 receptors in breast tumors promotes tumor progression via their downstream signaling pathways." (PMID 34572912, 2021). "Activation of the prolactin receptor (PrlR) and JAK2-STAT3 signaling pathway persists in ERα+/PR+ breast tumors to provide a critical survival signal during tumor recurrence." (PMID 27391074, 2016). "Our studies demonstrated that the PRLR-DBsAb redirected T cells to breast tumor cells and showed better anti-tumor activity rather than PRLR antibody." (PMID 32398042, 2020). "This suggested that tamoxifen could enhance the therapeutic efficacy of N8-PE24 even in estrogen receptor-negative, yet PRLR-positive, breast tumor cells." (PMID 38898487, 2024).
prostate carcinoma (22 papers, 2014 to 2025). A carcinoma that arises from epithelial cells of the prostate gland. "From a clinical perspective, the prognostic potential of PRLR provides a promising tool for risk stratification and personalized treatment of prostate cancer patients." (PMID 40978029, 2025). "It has been shown that PRL variants acting as competitive PRLR antagonists can efficiently down regulate PRLR signaling, cell survival, and/or proliferation in various breast or prostate cancer preclinical assays." (PMID 34358244, 2021). "The expression of PRL and PRLR has been reported to be higher in breast and prostate cancer than in their healthy counterparts and has been associated with increased risk of breast and prostate cancer and treatment resistance." (PMID 31862900, 2019). "PRL and expression of PRLR on tumor tissues have been strongly implicated in breast and prostate cancers for a considerable time via its mitogenic and angiogenic properties." (PMID 28223541, 2017). "In this study, we analyzed RNA sequencing data of prostate cancer patients from the TCGA database and identified that high PRLR expression was significantly associated with poor overall survival, suggesting its potential as a prognostic biomarker for prostate cancer." (PMID 40978029, 2025). "Of these, PRLR has been implicated in the pathology of breast and prostate cancer, NOX1 expression may be increased in prostate cancer with an important role in angiogenesis, cell growth, and tumor pathogenesis, and both AMH and PGF are reported as crucial genes in tumorigenesis." (PMID 35741849, 2022). "The selection of the 22RV1 cell line was driven by existing literature that reports the presence of PRLR, a factor deemed essential for delving into the molecular response to Osthole in prostate cancer." (PMID 40978029, 2025). "Studies have demonstrated that PRLR promotes the growth of prostate cancer cells by regulating multiple signaling pathways." (PMID 40978029, 2025). "To investigate the correlation between PRLR and prostate cancer, we identified differentially expressed genes between prostate cancer patients and normal individuals from public databases." (PMID 40978029, 2025). "Overexpression of PRL and/or PRLR were also described in glioblastoma, gynecological cancers, prostate cancer among other tumor types, reinforcing the notion of PRL:PRLR axis as a broad neoplastic feature providing proliferation and/or survival signaling." (PMID 37208719, 2023). "Elevated carboxypeptidase-D played an anti-apoptotic activity in prostate cancer, which is inhibited by combined prolactin receptor and androgen receptor targeting." (PMID 35686102, 2022). "Previous studies have found that PRLR plays an important role in pancreatic cancer, ovarian cancer, prostate cancer, Hodgkin’s lymphoma, prolactinoma, and BC." (PMID 36556307, 2022). "The role of prolactin and prolactin receptor has been most well studied in breast and prostate cancer." (PMID 31795960, 2019). "In prostate cancer treatment, the PRLR and JAK2/STAT3 signaling pathways are crucial targets." (PMID 40978029, 2025). "While Osthole might influence other pathways, such as PI3K/AKT, our analysis and experiments emphasize the PRLR - JAK2/STAT3 pathway’s key role in Osthole’s anti - prostate cancer effects." (PMID 40978029, 2025). "This significant downregulation of the PRLR protein indicates that Osthole may modulate the expression of key receptors involved in prostate cancer progression." (PMID 40978029, 2025). "To substantiate our hypothesis empirically, we performed western blot analysis, which demonstrated a marked reduction in the expression levels of PRLR in the 22RV1 prostate cancer cell line following treatment with Osthole." (PMID 40978029, 2025). "However, our research also revealed that Osthole can exert anti-prostate cancer effects by binding to PRLR, thereby inhibiting the JAK2/STAT3 pathway." (PMID 40978029, 2025).